Y_RNA (Y RNA )
Gene: Miscellaneous RNA gene on chromosome 8 (38,744,020 to 38,744,131, forward strand). Ensembl gene ENSG00000207258.
Homologues: Orthologues: chimpanzee Y_RNA (100% identical), macaque Y_RNA (86% identical). Paralogues in human: Y_RNA (85% identical), RNY1P5 (84% identical), Y_RNA (84% identical), Y_RNA (83% identical), Y_RNA (82% identical), Y_RNA (81% identical), Y_RNA (80% identical), RNY1 (79% identical), Y_RNA (79% identical), RNY1P1 (78% identical), Y_RNA (78% identical), RNY1P6 (77% identical), and 95 more.